CASP4 (caspase 4)
Diseases named in the same sentence as CASP4 in open-access papers (continued):
Sharing a sentence is not in itself a finding about the gene and the disease.
cancer (continued). "In this study, we demonstrated that the exposure of cancer cells to sublethal doses of curcumin could promote DDP chemotherapeutic efficiency against NSCLC cells, in which the ER stress pathway mediated by the CHOP, ATF6, and caspase-4 plays an important role." (PMID 35754693, 2022). "Interestingly, CASP5 mutations are associated with cancers, while CASP1 and CASP4 mutations are not, suggesting a caspase‐5‐specific protective role against tumorigenesis that is in keeping with SASP‐driven senescence surveillance." (PMID 30916891, 2019). "The results presented here indicate that, although CASP4 may not be necessary for maintenance of AJs in A431-derived cancer cells, it plays an important role in restoring AJs formation after abrogation of E-cadherin adhesive function." (PMID 30531914, 2018). "Thus, the rare mutation rate and the ability to activate pyroptotic process of CASP4 in the SCGB3A2-inducded non-canonical inflammasome pathway could be utilized as a new strategy for human cancer therapy." (PMID 33452234, 2021). "Furthermore, our bioinformatic analysis of caspase -4, -9, and GSDME are well-established as cancer markers that are also involving in non-canonical pyroptotic mechanisms." (PMID 34659633, 2021).
bacterial infection (15 papers, 2015 to 2025). "Bacterial infections common during exacerbations activate caspase-4/5 through intracellular LPS detection, while cigarette smoke induces mitochondrial DNA release that activates the AIM2 inflammasome." (PMID 41476973, 2025). "While neutrophils primarily utilize NETosis for pathogen defense, they undergo significant pyroptosis during bacterial infections through caspase-4/5 activation pathways." (PMID 41476973, 2025). "Well-known inflammasome proteins, such as NLRP3 and NLRC4, and Casp4 are intracellular PRRs that induce pyroptosis during intracellular bacterial infections." (PMID 39951384, 2025). "It is also possible that CASP4 alters the ability of microglia to clear Aβ via modulation of actin dynamics as observed in response to bacterial infection of macrophages." (PMID 38326859, 2024). "While CASP4/11 can be expressed in resting cells, it is highly induced in response to bacterial infections." (PMID 35588457, 2022). "During primary bacterial infection, bacterial lipopolysaccharide (LPS) triggers autoproteolytic activation of caspase-4/5/11; active caspase-4/5/11 subsequently cleaves gasdermin D (GSDMD), stimulating the host immune defense." (PMID 34888685, 2022). "GBP1 acts a gatekeeper of microbe-induced macrophage apoptosis and pyroptosis, and IFNγ enhanced macrophage pyroptosis mediated by caspase-4 in a GBP1-dependent manner during bacterial infection, such as Shigella flexneri and Salmonella." (PMID 35682857, 2022). "Caspase-4/11 expression is therefore altered beyond bacterial infections, in this case during treatment with NSAIDs." (PMID 32103022, 2020). "Similarly, the reduced expression of ADA and SIRT2, both involved in cellular senescence and inflammation, emphasizes the importance of caspase-4 in maintaining cell death and metabolic homeostasis during bacterial infections." (PMID 40137780, 2025). "To explore whether 0909I promotes caspase-4-dependent non-canonical inflammasome activation in human intestinal epithelial cell lines., we extended the bacterial infection experiments to the wild-type and Caspase-4-/- Caco-2 and HT-29 cells." (PMID 30138458, 2018). "Therefore, in this review, we examine murine caspase-11 and human orthologs caspase-4 and -5 as a potential regulator(s) of anti-bacterial autophagy by promoting phagolysosomal fusion in response to bacterial infection." (PMID 26426007, 2015). "Whether the human NLRP1 inflammasome is also involved in ER stress-dependent caspase-4/5 activation and cell death in response to bacterial infections is currently under investigation." (PMID 26086088, 2015). "CASP4: caspase 4; an inflammatory caspase activated by GBP1 during bacterial infection." (PMID 40910070, 2025). "The non-canonical inflammasome, which includes caspase-11 in mice and caspase-4 and caspase-5 in humans, is upregulated during inflammatory processes and activated in response to bacterial infections to carry out pyroptosis." (PMID 38106412, 2023). "Caspase-1, but not caspase-4, controls pyroptosis- and ubiquitin-independent proteasomal degradation of UBE2L3 upon canonical and non-canonical inflammasome activation by sterile danger signals and bacterial infection." (PMID 28147281, 2017).
infectious disease (5 papers, 2015 to 2022). A disorder directly resulting from the presence and activity of a microbial, viral, or parasitic agent in humans. "Notably, this high expression was the case for Il-1ß, ISG15, and CASP4, which are crucial for infectious diseases." (PMID 26159724, 2015). "Given the importance of caspase-4 and caspase-11 in inflammasome activation, SubAB may act as an anti-inflammasome factor to enhance STEC survival and worsen Stx-mediated infectious diseases." (PMID 35345462, 2022).
kidney diseases (4 papers, 2020 to 2024). "Pyroptosis is probably involved in kidney diseases through two pathways: the caspase-1-mediated canonical pathway and the caspase-4/5/11-mediated noncanonical pathway." (PMID 34007404, 2021). "The relatively higher expression of CASP4, CASP11, and GBPs compared to CASP1, PYCARD, and NLRP3, however, may suggest a more prominent role of non-canonical versus canonical inflammasome activation contributing to kidney disease." (PMID 38838223, 2024).
colonic polyps (1 paper, 2025). "For patients presenting with colonic polyps and progressing via the sCRC pathway, the detection of dysplastic tissue could also be aided by the addition of caspase-4 to current histopathological assessment, allowing earlier detection of high-risk individuals." (PMID 39866724, 2025). "Tissue samples from patients with CRC, colonic polyps, IBD-CRC, and sCRC were assessed by immunohistochemistry for caspase-4 expression in epithelial and stromal compartments." (PMID 39866724, 2025).
neurodegenerative disease (1 paper, 2025). A disorder of the central nervous system characterized by gradual and progressive loss of neural tissue and neurologic function. "Mitochondrial dysfunction is a well-established feature of neurodegenerative diseases, and our findings suggest that caspase-4 modulates mitochondrial dynamics in response to P. gingivalis-LPS in both SH-SY5Y and HMC3 cells." (PMID 40497980, 2025). "Our data further support the involvement of caspase-4 in the activation of various neuroinflammatory markers, including t-tau, VEGF, TGF-β, TNF-α, and IL-6, in response to P. gingivalis-LPS in both SH-SY5Y and HMC3 cells, all of which are associated with neurodegenerative diseases." (PMID 40497980, 2025).
vascular disorder (1 paper, 2017). A general term used to describe any disease affecting blood vessels]. "Complexes such as Bcl3/NF-kappaB2 complex (governed by BCL3 and NFKB2), vacuolar lumen (governed by CLN5), IPAF inflammasome complex (CASP1, CASP4, NLRC4) help to understand the involvement of inflammation and vascular disorder in AD." (PMID 28199395, 2017).
CASP4 also shares sentences with these, for which no sentence is quoted: diabetes (4 papers); adenocarcinoma (3); cervical cancer (3); cognitive decline (3); bladder cancer (2); chronic kidney disease (2); colorectal tumor (2); fibrosis (2); inflammation (2); pulmonary arterial hypertension (2); renal cell carcinoma (2); rheumatoid arthritis (2); abdominal aortic aneurysm (1); amyotrophic lateral sclerosis (1); ankylosing spondylitis (1); Ataxia-telangiectasia-like disorder 1 (1); autoimmune disease (1); brucellosis (1); chronic liver failure (1); chronic periodontitis (1); edema (1); emphysema (1); endometrial carcinoma (1); esophageal cancer (1); gouty arthritis (1); HCMV infection (1); heart transplant (1); hematologic disorder (1); Hepatic fibrosis (1); Hypervolemia (1).
A further 29 diseases each share a sentence with CASP4 in 1 paper.